IL6R (interleukin 6 receptor)
Diseases named in the same sentence as IL6R in open-access papers (continued):
Sharing a sentence is not in itself a finding about the gene and the disease.
depression (continued). "However, the adjusted OR for linear trend for association between IL6R genotype and severe depression and/or psychosis remained statistically significant after adjusting for potential confounders; adjusted OR = 0.66 (95% CI, 0.45–0.99); P-value = 0.046." (PMID 29197507, 2018). "The IL-6/IL-6R pathway could be causally linked to depression." (PMID 34135474, 2021). "While our findings suggest that altered activity of the IL-6/IL-6R pathway could be a risk factor for depression, disentangling the issue of IL-6 classic vs trans-signalling is beyond the scope of population genomics approaches as full effects of genetic variants used are unknown." (PMID 34505025, 2021). "Altered activity of the IL-6/IL-6R pathway could be a risk factor for depression." (PMID 34505025, 2021). "The pathogenesis of depression is correlated with inflammation, specifically the IL-6/IL-6R pathways; peripheral blood levels of inflammatory markers increased during the acute episodes of depression." (PMID 41274868, 2025). "Conversely, LDL-C depression is strongly responsive to IL-6R blockade, with LDL-C levels likely returning to the predisease set point." (PMID 38795859, 2024). "Future studies need to investigate the role of IL6R in the pathogenesis of depression, as well as the interactions between IL6R and sarilumab or satralizumab." (PMID 36009493, 2022). "Our findings propose IL6R as the most promising target gene for depression due to IL6R exhibiting the highest functional annotation score and its validation in ClinicalTrial.gov and PubMed databases." (PMID 36009493, 2022). "IL6R was one of the target genes with the highest functional annotation score and was a highly promising target in the treatment of depression." (PMID 36009493, 2022). "Using genetic variants in the IL6R and CRP gene loci, we have found that higher genetically predicted IL-6 activity was associated with increased risk of depression, but higher genetically predicted CRP levels were associated with decreased risk of depression." (PMID 34505025, 2021). "Our findings lend support to RCTs testing immunotherapies targeting the IL-6/IL-6R pathway for patients with depression." (PMID 34505025, 2021). "In this study, we measured serum levels of tumor necrosis factor‐α, interleukin 6, and soluble interleukin 6 receptor after major depressive disorder patients underwent antidepressant therapy." (PMID 32162496, 2020). "Soluble-IL6R circulates at elevated levels in various diseases, including major depressive disorder and bipolar disorder." (PMID 31362361, 2019). "Based on human population-based data our findings provide further evidence that the IL-6/IL6R pathways are involved in pathogenesis of severe depression and psychosis." (PMID 29197507, 2018). "The field now needs RCTs of cytokine modulators targeting IL-6/IL6R for patients with depression and psychosis, specifically those with evidence of inflammation, to translate these results into benefits for patients." (PMID 29197507, 2018). "Based on a small number of cases the findings need replication in other samples, but provide further evidence that the IL-6/IL6R pathways are involved in pathogenesis of severe depression and psychosis." (PMID 29197507, 2018). "Out of 3251 participants with data on IL6R genotype and diagnosis of severe depression and/or psychosis, 173 were related (IBD cut off = 0.05)." (PMID 29197507, 2018). "Data on CIS-R depression total score at age 18 years and IL6R genotype were available for 3400 participants." (PMID 29197507, 2018). "We explored the relationship of IL6R genotype with diagnosis of severe depression only and psychotic disorder only." (PMID 29197507, 2018). "Overall, these findings indicate that knocking down IL‐6 in hippocampal microglia and IL‐6R in hippocampal astrocytes, along with inhibition of the IL‐6 trans‐signaling pathway using sgp130, significantly alleviates depression‐like behaviors and reduces astrocyte atrophy in CSDS mice." (PMID 39888279, 2025).
depression (continued). "Notably, the knockdown of IL‐6 in hippocampal microglia and IL‐6R in hippocampal astrocytes significantly improved astrocyte survival and alleviated anxiety‐ and depression‐like behaviors induced by CSDS." (PMID 39888279, 2025). "In addition, the IL‐6/IL‐6R pathway represents a potential target for depression treatment, offering valuable insights into depression therapy." (PMID 39888279, 2025). "Hypermethylation of IL6R was associated with low expression in the no depression group and high expression in the depression group." (PMID 41274868, 2025). "Consequently, the IL‐6/IL‐6R pathway has emerged as a promising target for the treatment of depression." (PMID 39888279, 2025). "Our results indicate that the IL-6/IL-6R pathway may represent a novel therapeutic target for schizophrenia and depression." (PMID 34280516, 2021). "Findings from MR analyses are consistent with a role of altered activity of the IL-6/IL-6R pathway in depressive symptoms, suggesting that this pathway could be a promising, new therapeutic target for depression." (PMID 34505025, 2021). "We have also previously reported that IL-6R variants associated with higher serum IL-6 levels (but decreased IL-6R activity) and CRP variants associated with higher CRP levels are both associated with increased risk of depression in the UK Biobank." (PMID 34135474, 2021). "Furthermore, a genetic variant in the IL6R gene (Asp358Ala; rs2228145 A>C), which is known to dampen down inflammation by impairing IL-6R signalling, was previously reported to be protective for severe depression." (PMID 30886334, 2020). "Secondary analysis of existing RCTs suggests mAb against specific inflammatory cytokines, such as IL-6/IL-6R, could be helpful for depression." (PMID 31258105, 2019). "We are conducting an RCT of tocilizumab (anti-IL-6R mAb) for patients with depression." (PMID 31258105, 2019). "The findings provide further evidence that the IL-6/IL6R pathways are involved in pathogenesis of severe depression and psychosis, and may be novel therapeutic targets." (PMID 29197507, 2018). "Treatment with a monoclonal antibody against IL-6 receptor (IL6R) may improve symptoms of depression and schizophrenia." (PMID 29197507, 2018). "BMI is related to C-reactive protein, and a high level of C-reactive protein is associated with depression, confirming the assumption that other causes of peripheral inflammation (e.g., the interleukin 6 receptor [IL6R]) may affect the development of depression." (PMID 41274868, 2025). "Thus, managing IL-6/IL-6R levels in the circulatory system could control both inflammation and depression." (PMID 41274868, 2025). "Furthermore, another study found that an IL6R functional variant could reduce inflammation, and high serum levels of IL-6/IL6R can increase the severity of depression." (PMID 41274868, 2025). "Although Asp358Ala is associated with serum IL-6 and soluble IL6R levels, it is not clear whether the effect of Asp358Ala on risks of severe depression and/or psychosis is mediated by specifically serum IL-6, soluble IL6R or membrane-bound IL6R." (PMID 29197507, 2018). "In the controls, PON1 rs705381 was associated with compulsions, PON1 rs705379 with social anxiety, depression, anxiety, and aggression, PON1 rs854560 with obsessions, anxiety, and social phobia, and IL6R rs2228145 with aggression." (PMID 38275640, 2023). "Additionally, CSDS significantly increases the release of IL‐6, and knockdown of IL‐6 in hippocampal microglia and IL‐6R in hippocampal astrocytes significantly enhances astrocyte survival while alleviating CSDS‐induced anxiety‐ and depression‐like behaviors." (PMID 39888279, 2025). "IL-6 encodes a kind of cytokine, which plays a role in the process of inflammatory response and B-cell maturation by binding to receptors IL6R and IL6ST, whose dysregulation can precipitate multiple events relevant to depression, such as serotonin depletion and neurodegenerations." (PMID 39408591, 2024).
depression (continued). "Not all studies, however, were able to find increased serum sIL-6R levels or lymphocyte IL-6R mRNA expression in depression." (PMID 29103192, 2018).
Arthritis (43 papers, 2004 to 2026). Inflammation of a joint. "Soluble Interleukin-6 receptor (sIL-6R) mediated trans-signaling is an important pro-inflammatory stimulus associated with pathological conditions, such as arthritis, neurodegeneration and inflammatory bowel disease." (PMID 28276471, 2017). "It is therefore of interest that anti-interleukin-6 receptor antibody has been shown to be clinically beneficial for the treatment of arthritis and Crohn's disease and its action is associated with the suppression of C-reactive protein." (PMID 15570310, 2004). "An anti-IL-6R monoclonal antibody tocilizumab has been applied in clinical treatment for irAEs, including colitis, arthritis and irAEs related cytokine release syndrome." (PMID 40519900, 2025). "The up‐regulation of IL‐6R weakened the effect of YTHDF2 on the decrease of arthritis severity score in CIA mice." (PMID 40548546, 2025). "Regarding the immune checkpoint inhibitors, there is an increase in TIM-3 in peripheral lymphocytes from arthritis rheumatoid patients treated with anti-IL-6R antibody." (PMID 38928437, 2024). "Technical advances in special transcriptomics will help us understand the spatiotemporal relationships among OSM+ macrophages, OSMR+ fibroblasts, IL-6+ fibroblasts and IL-6R+ macrophages in the inflamed synovium during the course of arthritis in future." (PMID 39080781, 2024). "Lastly, mice studies have shown that pretreatment of mesenchymal stem/stromal cells with soluble IL6R can enhance the therapeutic effects of mesenchymal stem/stromal cells in arthritis inflammation." (PMID 39039335, 2024). "Treating the 5-mo-old DNase II−/−STINGS365A/S365A mice with anti–IL-6R reduced the arthritis score and the expression of IL-6 and MMP-3 but did not reduce the expression of TNF-α, CXCL1, and CXCL2." (PMID 34901991, 2022). "Siltuximab and tocilizumab, targeting IL-6 and the IL-6R respectively, have been approved for the treatment of Castleman disease (siltuximab) and arthritis (tocilizumab)." (PMID 35118141, 2021). "At the time of the survey, 30% of patients were on no immunosuppressive medications for their irAE, 41% were on corticosteroids and 12% were on a biological agent (TNF or IL-6R inhibitor) for arthritis." (PMID 33067320, 2020). "For example, although many patients with arthritis benefit from anti-IL6R therapy, this benefit is usually restricted to an incomplete decrease in disease activity, suggesting that other inflammatory pathways are in play." (PMID 31156640, 2019). "Remarkably, mice treated with the late anti-IL-6R/anti-IL-21 combination therapy show a clear protective effect on arthritis incidence; only 60% of those mice developed arthritis before the end of the study (day 30)." (PMID 28158305, 2017). "Blockade of IL-6R significantly attenuated serum-transferred TIARP−/− arthritis with diminished neutrophil recruitment in joints." (PMID 27995997, 2016). "We found that IL-6 regulated the expression of SLC19A1, so we also studied the effect of concomitant use of MTX and anti-IL-6 receptor (IL-6R) antibody in this arthritis model." (PMID 22546471, 2012). "This preference for tocilizumab may result from the increasing use of interleukin-6 receptor inhibitors for the treatment of other refractory irAEs such as arthritis and pneumonitis." (PMID 36294298, 2022). "Interestingly, arthritis incidence was further reduced when mice were treated with the anti-IL-6R/anti-IL-21 combination therapy, resulting in only 40% of mice developing arthritis." (PMID 28158305, 2017). "Indeed, studies with monoclonal antibodies designed to target IL-6 receptors (IL-6R) reported an attenuation of collagen-induced arthritis in mice, as well as in human RA." (PMID 28587618, 2017). "However, the present results have demonstrated that blockade of IL-6R seems to have a therapeutic effect on serum-transferred arthritis with clear protection of neutrophil recruitment in joints of TIARP−/− mice." (PMID 27995997, 2016).
Arthritis (continued). "Intra-articular administration of IL-6 into the joints of IL-6-deficient mice did not lead to arthritis, but a soluble IL-6/IL-6R fusion protein caused joint swelling and other symptoms of arthritis." (PMID 19368720, 2009). "Furthermore, studies suggesting an involvement of IL-6 in the induction of Th17 cells in arthritis models have been reported: anti-IL-6R antibody suppressed the onset of arthritis in G6PI-induced and collagen-induced arthritis models and concomitantly inhibited the appearance of Th17 cells." (PMID 22046525, 2011). "Currently, there are emerging pharmaceuticals, including JAK inhibitors, anti-IL-6R agents, and anti-IL-17A antibodies, that show promise in the treatment of ICI-arthritis." (PMID 39122457, 2024). "To determine the role of IL-6 in the development of arthritis, we treated 6-wk-old DNase II−/−STINGS365A/S365A mice with a neutralizing antibody against the IL-6 receptor (anti–IL-6R) once a week." (PMID 34901991, 2022). "Th17 activation and arthritis activity, such as joint swelling of CIA mice were inhibited by the treatment of anti-IL-6R antibody." (PMID 34532317, 2021). "Also in comparison with mice treated solely with anti-IL-6R antibodies, a compound currently used to effectively treat RA patients and known as Tocilizumab (JW Pharmaceutical, Seoul, South Korea), the combination treatment proved to be much more potent in preventing arthritis development." (PMID 28158305, 2017). "Indeed, when treating mice with both anti-IL-6R antibodies and sIL-21R.Fc either during the induction phase of arthritis (day 0) or in a later stage of the disease (day 21), arthritis incidence levels could potently be reduced, confirming the therapeutic potency of this strategy in a RA mouse model." (PMID 28158305, 2017). "However, serum-transferred arthritis is a neutrophil-dependent and T cell-independent model of RA19, suggesting that the effect of anti-IL-6R Abs in the development of serum-transferred arthritis in TIARP−/− mice might be distinct from T helper cell differentiation." (PMID 27995997, 2016). "Anti-IL6R therapy reduced AtpTreg levels, corresponding with improved arthritis outcomes and quality of life, without compromising anti-tumor immunity." (PMID 42118587, 2026). "In addition, there is another FDA approved treatment for patients with arthritis and B cell acute lymphoblastic leukemia under CAR-T therapy, Tocilizumab, which recognizes IL-6R and disrupts the signaling cascade." (PMID 38313431, 2023). "Tocilizumab is a humanized anti-IL6R antibody with FDA approval for arthritis but not yet for any cancer immunotherapy applications." (PMID 35260569, 2022). "Furthermore, iRhom2-dependent trafficking of the IL-6R sheddase ADAM17 and its activity on myeloid cells was shown to be involved in development of experimental arthritis in mice." (PMID 31694340, 2019). "Surprisingly, administration of IL-6R Ab, but not control Ab, resulted in significantly attenuated the development of serum-transferred arthritis in TIARP−/− mice." (PMID 27995997, 2016). "This holds true when treatment was initiated early during arthritis development, but especially when first therapeutic injections were administered in a later stage of the disease, where the anti-IL-6R antibodies could not prevent disease onset." (PMID 28158305, 2017). "Interestingly, neither anti-IL-6R antibodies, nor anti-IL-21 therapy as single treatments could reduce arthritis severity in the severe and progressive collagen-induced arthritis model." (PMID 28158305, 2017). "IL-6 appears to promote arthritis primarily via trans signaling, likely because synovial fibroblasts and activated CD4+ T cells do not express sufficient IL-6R to respond to IL-6 alone." (PMID 31156640, 2019). "In addition, study demonstrated that the absence of IL-6 induces complete protection against arthritis in CIA mice and an anti-mouse IL-6R monoclonal antibody inhibits development of arthritis in CIA mice." (PMID 27122657, 2016).